AATF (apoptosis antagonizing transcription factor)
Diseases named in the same sentence as AATF in open-access papers (continued):
Sharing a sentence is not in itself a finding about the gene and the disease.
cancer (continued). "To clarify the expression level of AATF across cancers, we first analyzed the TIMER2.0 tool, and 21 of the 33 tumors had tumor and adjacent normal tissue data." (PMID 36275893, 2022). "Fourteen of the mutated genes in this tumor are involved in metabolism (endogenous molecules as well as drugs), small molecule biochemistry, and cancer: AATF, ATF71P, CRIPAK, CROCC, CYP2A6, DOCK5, GPAT2, KRTAP4–9, LSM14A, MUC2, MYO1F, RHOQ, SUFU, and UTRN." (PMID 29259192, 2017). "The lower molecular weight AATf was likely generated by proteolytic digestion of the abundant AAT within the cancer microenvironment." (PMID 19709441, 2009). "Here we have screened the entire coding region of AATF in affected index cases from 121 Finnish cancer families for germline defects, using conformation sensitive gel electrophoresis and direct sequencing." (PMID 20025740, 2009). "Notably, GSEA indicated enrichments in DNA strand elongation and DNA replication processes, suggesting a crucial role for AATF in facilitating the replication machinery essential for cancer cell growth." (PMID 39911629, 2025). "Furthermore, GSEA indicated the activation of pre-replication complexes and extended telomerase activity, suggesting AATF’s influence on telomere maintenance, which is critical for sustaining cancer cell proliferation." (PMID 39911629, 2025). "This suggests that AATF expression might be transiently upregulated and downregulated in cancer cells treated repeatedly with VBL." (PMID 39408701, 2024). "In the absence of a comprehensive description of AATF's molecular properties in human cancer, the role of AATF in pan-cancer research is currently unknown." (PMID 36275893, 2022). "Additionally, various potential biological functions and common features of AATF across cancers were analyzed and verified to explore the potential molecular mechanism of AATF across cancers." (PMID 36275893, 2022). "Across a variety of cancers, the expression of AATF was highly correlated with immune infiltration and immune checkpoint markers, which indicates that AATF may be a target for immunotherapy." (PMID 36275893, 2022). "Importantly, this knowledge will—in the long term—be the key to exploiting a potential modulation of AATF in the clinical setting with a focus on cancer, cardiovascular disease, and organ protection from genotoxic and oxidative stress." (PMID 32587828, 2020). "Since rRNA transcription and ribosome biogenesis are required for cell growth and division, AATF-driven increase in ribosome density may contribute to the proliferative potential of malignant tumors." (PMID 32587828, 2020). "Thus, it became evident that TACE could be an attractive candidate to explore its possible role in AATF‐mediated metabolic inflammation to cancer." (PMID 38558505, 2024). "Our analysis showed that AATF, LGALS3, and SRC are up regulated in 8/13 of cancer models, and CDC2L2, E2F6, LGALS9, PDCD8, RELB, TRADD, and TRAF2 in 7/13." (PMID 19402918, 2009). "Aside from cancer, a number of studies also revealed putative roles of AATF in non-malignant, e.g., cardiovascular diseases." (PMID 32587828, 2020).
tumor (12 papers, 2017 to 2025). "In this study, we aim to identify the key role of apoptosis antagonizing transcription factor (AATF) in tumor angiogenesis and its underlying mechanisms in HCC." (PMID 37361585, 2023). "Our findings in NAFLD-associated HCC showed that AATF expression was upregulated, whereas knocking down AATF significantly reduced tumor burden and metastasis in a mouse xenograft model." (PMID 37361585, 2023). "Conversely, AATF expression was positively correlated with Th2 cells, indicating that high AATF levels may facilitate the recruitment or activation of these immune cell populations, which can be associated with tumor progression." (PMID 39911629, 2025). "Elevated levels of AATF correlate with increased tumor invasiveness and metastasis, as well as decreased patient survival, indicating its potential role in tumorigenesis and progression." (PMID 39911629, 2025). "AATF expression was significantly higher in tumor tissues (mean ± SD: 3.62 ± 1.21) compared to adjacent tissues (mean ± SD: 1.18 ± 0.54, p < 0.001)." (PMID 39911629, 2025). "The strong positive correlation between AATF expression and immune infiltration of specific cell types suggests its potential role in modulating the tumor microenvironment." (PMID 39911629, 2025). "AATF is an apoptosis‐antagonising transcription factor, which has been shown to be required for tumour cell survival." (PMID 39428382, 2024). "The levels of AATF were found to be significantly related to the pathological stages and tumor grades of HCC." (PMID 37361585, 2023). "We have previously, for the first time, unraveled the role of AATF as a potential driver of HCC in NAFLD and demonstrated that the knockdown of AATF inhibited tumor growth and metastasis." (PMID 37361585, 2023). "Another approach would be the generation of liver-specific AATF knockout mice that can be used to induce HCC and examine the role of AATF in tumor progression, angiogenesis, and metastasis." (PMID 37361585, 2023). "We also compared differences in AATF protein phosphorylation levels between normal and primary tumor tissues." (PMID 36275893, 2022). "According to the study, AATF promoter methylation levels were significantly lower in 8 tumor tissues than in normal tissues, potentially correlating with the high expression of AATF in these tumors." (PMID 36275893, 2022). "This study helps us to understand the role of AATF in tumorigenesis from the perspective of clinical tumor samples." (PMID 36275893, 2022). "Comparing AATF expression in tumors and adjacent normal tissues, AATF was elevated in 15 tumors and decreased in 1 tumor (P < 0.05)." (PMID 36275893, 2022). "Recently, Che-1/AATF has emerged as a modulator of tumor cell survival and tumor progression, and silencing of AATF can be employed to trigger BC cell apoptosis." (PMID 33420414, 2021). "Overexpression of a phospho-mimicking, hyperactive AATF mutant resulted in tumor resistance toward anti-neoplastic therapy." (PMID 32587828, 2020). "We also noted that some proliferation-associated genes in tumor cells were also significantly regulated by CRNDE knockdown, including IGFBP4, ANXA1, KLF6, AATF, and IFI16." (PMID 33298855, 2020). "Further investigation into these dynamics may elucidate AATF’s potential as a therapeutic target for enhancing anti-tumour immunity in OSCC." (PMID 39911629, 2025). "AATF, an apoptosis‐antagonising transcription factor, is crucial for tumour cell survival." (PMID 39428382, 2024).
tumor (continued). "Our study reports the first evidence that the therapeutic strategy based on the inhibition of AATF to disrupt tumor angiogenesis may serve as a promising approach for HCC treatment." (PMID 37361585, 2023). "The OS and DFS of AATF in all TCGA tumor patients were analyzed using GEPIA2." (PMID 36275893, 2022). "As a result of AATF depletion, tumor cells are sensitive to anticancer drugs, suggesting that AATF might be a potential therapeutic target." (PMID 36275893, 2022). "AATF is also closely related to tumor survival and prognosis." (PMID 36275893, 2022). "However, how AATF affects tumor survival and prognosis requires further research." (PMID 36275893, 2022). "We identified high levels of AATF in human HCC tissues compared to adjacent normal liver tissues, and the expression was found to be correlated with the stages and tumor grades of HCC." (PMID 37361585, 2023). "Promoter analysis reveals that AATF can bind SREBP-1c to regulate HCC cell proliferation, migration, colony formation, and xenograft tumor growth and metastasis." (PMID 35912181, 2022). "Immunohistochemistry findings provided spatial insights into AATF expression, showing predominant localization within tumor cells compared to adjacent non-cancerous tissues." (PMID 39911629, 2025). "Collectively, multiple upstream molecules, such as HDGF, AATF, ZHX2, ACSL4, SPIN, HBx, HDAC8, and STAT5, can regulate SREBP-1 expression, activation, and stability to promote HCC proliferation, invasion, and migration for tumor growth and metastasis." (PMID 35912181, 2022). "Specifically, AATF expression exhibited a negative correlation with mast cells, immature dendritic cells (iDCs), and TH17 cells, suggesting that elevated AATF levels may suppress the infiltration of these immune cells, which are crucial for anti-tumor immunity." (PMID 39911629, 2025).
infection (1 paper, 2021). The state of being infected such as from the introduction of a foreign agent such as serum, vaccine, antigenic substance or organism. "Additionally, AATF is specifically targeted by HIV to impair cellular responses to infection." (PMID 34541469, 2021).
AATF also shares sentences with these, for which no sentence is quoted: prostate carcinoma (2 papers); acute kidney injury (1); acute lymphoblastic leukemia (1); Autosomal dominant tubulointerstitial kidney diseases (1); bacterial infection (1); bladder cancer (1); cardiovascular diseases (1); colon adenocarcinoma (1); esophageal carcinoma (1); gastric cancer (1); Hashimoto thyroiditis (1); lung squamous cell carcinoma (1); lymphoma (1); mesothelioma (1); multiple myeloma (1); oral squamous cell carcinoma (1); ovarian serous cystadenocarcinoma (1); pancreatic adenocarcinoma (1); rectum adenocarcinoma (1); retinoblastoma (1); testicular germ cell tumor (1); thymoma (1); thyroid carcinoma (1); uterine corpus endometrial carcinoma (1); Wilms tumor (1).